C1orf74 (chromosome 1 open reading frame 74)
Synonyms: FLJ25078; URLC4
Tractability: Antibody: the Human Protein Atlas places it where antibodies can reach.
Gene: Protein-coding gene on chromosome 1 (209,779,208 to 209,784,620, reverse strand). Ensembl gene ENSG00000162757.
Subcellular location (Human Protein Atlas): Cytosol; Plasma membrane
Gene Ontology:
Molecular function: protein binding
Genetic constraint (gnomAD): Loss-of-function variants: 6 observed, 10.16 expected, observed/expected ratio (o/e) 0.59, 90% interval 0.32 to 1.16. The upper end of that interval is the gene's LOEUF score, 1.16, which puts it in group 5 of 6, group 1 being the genes least tolerant of losing a copy. Missense variants: 291 observed, 333.19 expected, observed/expected ratio (o/e) 0.87, 90% interval 0.79 to 0.96. Synonymous variants: 121 observed, 140.25 expected, observed/expected ratio (o/e) 0.86, 90% interval 0.74 to 1.
Homologues: Orthologues: chimpanzee C1H1orf74 (99% identical), macaque C1H1orf74 (96% identical), pig C1orf74 (84% identical), rabbit C1orf74 (78% identical), mouse A130010J15Rik (77% identical), rat C13h1orf74 (76% identical), dog C1orf74 (73% identical), tropical clawed frog c2h1orf74 (35% identical), zebrafish zgc:112163 (34% identical).
Diseases named in the same sentence as C1orf74 in open-access papers:
C1orf74 is named in the same sentence as 12 diseases in open-access papers, as found by Europe PMC text mining. Sharing a sentence is not in itself a finding about the gene and the disease. The quoted sentences say what the papers report.
lung adenocarcinoma (2 papers, 2022 to 2023). A carcinoma that arises from the lung and is characterized by the presence of malignant glandular epithelial cells. "A recent research study reported that higher expression of C1orf74 was associated with poorer prognosis in lung adenocarcinoma patients." (PMID 37947608, 2023). "C1orf74, also known as URCL4, has been reported to have higher expression and be associated with poor prognosis in lung adenocarcinoma patients, and its role in regulation of the EGFR/AKT/mTORC1 pathway has been recently elucidated." (PMID 37947608, 2023). "An extensive literature search identified only one publication suggesting a role for C1orf74 in regulating EGFR/AKT/mTORC1 signaling lung adenocarcinoma cells." (PMID 37947608, 2023). "Our findings are in agreement with the previous report of C1orf74 in lung adenocarcinoma, which is not hormonally regulated like cervical cancer, but showed a correlation of C1orf74 with the regulation of the EGFR/AKT/mTORC1 pathway." (PMID 37947608, 2023).
thymoma (2 papers, 2015 to 2023). A neoplasm arising from the epithelial cells of the thymus. "C1orf74 was especially found to be significantly overexpressed in cervical cancers (CESCs), lung squamous cell carcinomas (LUSCs), and thymoma (THYM)." (PMID 37947608, 2023).
cervical cancer (1 paper, 2023). A primary or metastatic malignant neoplasm involving the cervix. "In the current study, we used publicly available data and experimental validation of C1orf74 gene expression and its association with prognosis in cervical cancer patients." (PMID 37947608, 2023). "Collectively, our study indicates that higher expression of the C1orf74 gene caused by hypomethylation of its promoter is associated with poor overall survival in cervical cancer patients." (PMID 37947608, 2023). "We evaluated the expression of the C1orf74 gene in patients with cervical cancer and assessed its association with various pathways to further correlate the expression patterns with clinical outcomes with further progression of the disease." (PMID 37947608, 2023). "Analysis of mRNA expression profiles of C1orf74 in cervical cancer TCGA datasets using multiple online resources like UALCAN, GEPIA, TNMplot, and OncoDB revealed that cervical tumors have significantly higher expression levels compared to other cancers." (PMID 37947608, 2023). "In this study, we obtained the top 25 genes with the highest correlation with C1orf74 in cervical cancer from UALCAN for further analysis to define the possible role of C1orf74 in the development of cervical cancer." (PMID 37947608, 2023). "qPCR analysis also demonstrated higher expression of C1orf74 in HPV-positive cervical cancer cell lines and most cervical cancer patients." (PMID 37947608, 2023). "We observed significantly higher expression of C1orf74 in HPV-positive cervical cancer cell lines HeLa, SiHa, and Ca Ski." (PMID 37947608, 2023). "This enrichment of the pattern of the PI3K-Akt pathway positively correlated with C1orf74 expression in cervical cancer." (PMID 37947608, 2023). "Combining this information with our understanding of C1orf74 protein function, we infer that C1orf74 plays a role in promoting the development of cervical cancer." (PMID 37947608, 2023). "The expression levels of C1orf74 in all histological subtypes of cervical cancers were significantly higher than the normal control tissues." (PMID 37947608, 2023). "In the current study, we analysed the expression and prognostic value of C1orf74 in cervical cancer." (PMID 37947608, 2023). "RNA-Seq data from the TNMplot database revealed higher expression of the C1orf74 gene in cervical tumors and metastatic cervical cancer samples compared to normal tissue." (PMID 37947608, 2023). "Promoter DNA methylation levels of C1orf74 in the cervical cancer TCGA dataset were acquired using UALCAN." (PMID 37947608, 2023). "Further analysis found that the promoter methylation level of C1orf74 was consistently lower in all stages of cervical cancer compared to normal tissues." (PMID 37947608, 2023). "The results suggested that the expression of C1orf74 was higher in HPV-positive cervical cancer cell lines compared to normal cells and the HPV-negative cancer cell line C-33A derived from a uterine tumor." (PMID 37947608, 2023). "The interaction of cervical cancer’s EGFR/AKT/mTORC1 signaling pathway with HPV infection leading to cervical cancers forms a strong plinth to determine the role of C1orf74 in oncogenesis and further progression of the disease." (PMID 37947608, 2023). "The promoter methylation levels of the C1orf74 gene in cervical cancer tissues were lower compared to normal cervical tissues (p < 0.05)." (PMID 37947608, 2023). "We found that C1orf74 expression in HPV-positive cervical cancers was significantly higher compared to HPV-negative cervical cancers." (PMID 37947608, 2023). "Data from TNMplot revealed that mRNA expression of the C1orf74 gene in primary tumor tissues, as well as metastatic tissues from cervical cancer patients, was significantly higher compared to normal cervical tissues." (PMID 37947608, 2023). "We then evaluated the levels of C1orf74 expression in tumors derived from 25 cervical cancer patients using RT-qPCR." (PMID 37947608, 2023).
cervical cancer (continued). "We also observed that HPV-positive cervical cancers showed higher expression of C1orf74 than the HPV-negative group of cervical cancers." (PMID 37947608, 2023). "Our study suggests that C1orf74 is a valuable prognostic marker for cervical cancer." (PMID 37947608, 2023). "It however remains unclear whether C1orf74 plays any role in metastasis in cervical cancer." (PMID 37947608, 2023). "Thus, C1orf74 is a novel prognostic marker in cervical cancer." (PMID 37947608, 2023). "Thus, C1orf74 presents a new prognostic marker and novel target for cervical cancer treatment." (PMID 37947608, 2023). "The selection of these specific cell lines was based on the need to compare the relative expression of C1orf74 mRNA in HPV-positive cervical cancer cell lines HeLa, SiHa, and Ca Ski versus the HPV-negative cervical cancer cell line C33A." (PMID 37947608, 2023). "Consistently, we found that the methylation levels of the C1orf74 promoter were lower in cervical cancer tissues than the normal tissues, and this reduced methylation was maintained across all stages of cervical cancer." (PMID 37947608, 2023). "However, we did not observe any significant difference in the expression of C1orf74 based on individual cervical cancer stages." (PMID 37947608, 2023). "Although the expression of C1orf74 was not significantly different among various stages of cervical tumors, our findings suggest that C1orf74 may be involved in the invasion and metastasis of cervical cancer." (PMID 37947608, 2023).
endocervical carcinoma (1 paper, 2023). A carcinoma that arises from epithelial cells of the endocervix. "The promoter methylation levels of C1orf74 in squamous cell carcinomas were found to be the lowest, followed by adenocarcinomas and endocervical carcinomas." (PMID 37947608, 2023).
lung carcinoma (1 paper, 2022). "As the AKT/mTORC1 signaling is a crucial signaling axis downstream of EGF receptor which has high mutation rate in lung cancers, we asked whether C1orf74 has any role in EGF-stimulated activities of AKT and mTORC1 in LUAD cells." (PMID 36032960, 2022).
squamous cell carcinoma (1 paper, 2023). A carcinoma arising from squamous epithelial cells. "Fusion transcripts of C1orf74 and neighboring IRF6 have been reported previously in squamous cell carcinomas." (PMID 37947608, 2023).
cancer (3 papers, 2022 to 2023). A tumor composed of atypical neoplastic, often pleomorphic cells that invade other tissues. "Although the present study, to the best of our knowledge, was the first to reveal C1orf74’s function, underlying mechanism as well as its association with cancer, there are some limitations exist." (PMID 36032960, 2022). "C1orf74 refers to protein encoded by C1orf74 (Chromosome 1 Open Reading Frame 74) gene located at 1q32.2, but its function is still unknown either in normal cells or cancer cells." (PMID 36032960, 2022). "Moreover, studying C1orf74’s role, mechanism and association with prognosis in other types of cancers will provide helpful evidences to completely understand C1orf74’s role in tumorigenesis." (PMID 36032960, 2022). "The gene expression profiles of C1orf74 across tumor and normal tissues were investigated using the GEPIA database to check the differential expression of C1orf74 among different cancers." (PMID 37947608, 2023). "Our findings can be extended to studies on the molecular mechanisms of C1orf74 in diverse cancers." (PMID 37947608, 2023). "The C1orf74 protein is found in both cytoplasm as well as plasma membrane but its function in normal and cancer cells remains unknown." (PMID 37947608, 2023). "The expression of C1orf74 was higher in most cancers compared to normal tissues." (PMID 37947608, 2023). "Moreover, it is worth to investigate C1orf74’s expression in other types of cancers, so that we can obtain the idea whether C1orf74’s upregulation is specific phenomenon in LUAD or common in most cancers." (PMID 36032960, 2022). "C1orf74 is a novel protein with unknown function either in normal cells or cancer cells." (PMID 36032960, 2022). "To understand how C1orf74 to affect LUAD progression, we performed in vitro experiments to investigate its effects on some of the hallmarks of cancer cells." (PMID 36032960, 2022).
tumor (3 papers, 2022 to 2023). "In the present report, we observed that C1orf74 was highly expressed in LUAD tumor tissues and its high expression is associated with unfavorable prognosis of patients with LUAD." (PMID 36032960, 2022). "The results suggested that, the high expression of C1orf74, HK2, SLC22A3, SNX10 and URB2 and Neutrophils, as well as the low expression of RASSF5 and CD8+ T cells was related to the poor prognosis of CC patients, which might serve as the key prognostic biomarkers of tumor." (PMID 36354693, 2022).
C1orf74 also shares sentences with these, for which no sentence is quoted: adenocarcinoma (1 paper); cervical tumors (1); lung squamous cell carcinomas (1); uterine tumor (1).